RP1 (RP1 axonemal microtubule associated)
Description:
Microtubule-associated protein regulating the stability and length of the microtubule-based axoneme of photoreceptors. Required for the differentiation of photoreceptor cells, it plays a role in the organization of the outer segment of rod and cone photoreceptors ensuring the correct orientation and higher-order stacking of outer segment disks along the photoreceptor axoneme (By similarity).
Synonyms: ORP1; DCDC4A
Tractability: No criterion of Open Targets' tractability assessment is met for any kind of drug.
Gene: Protein-coding gene on chromosome 8 (54,509,422 to 54,871,720, forward strand). Ensembl gene ENSG00000104237.
Subcellular location: Cytoplasm, cytoskeleton, cilium axoneme; Cell projection, cilium, photoreceptor outer segment
Subcellular location (Human Protein Atlas): Mid piece
Gene Ontology:
Molecular function: protein binding; microtubule binding
Biological process: axoneme assembly; photoreceptor cell development; photoreceptor cell maintenance; photoreceptor cell outer segment organization; phototransduction, visible light; retina development in camera-type eye; retinal cone cell development; retinal rod cell development; visual perception; intracellular signal transduction; response to light stimulus
Cellular component: photoreceptor connecting cilium; photoreceptor inner segment; axoneme; microtubule associated complex; photoreceptor outer segment; ciliary tip; cilium; photoreceptor cell cilium
Genetic constraint (gnomAD): Loss-of-function variants: 18 observed, 18.44 expected, observed/expected ratio (o/e) 0.98, 90% interval 0.67 to 1.45. The upper end of that interval is the gene's LOEUF score, 1.45, which puts it in group 5 of 6, group 1 being the genes least tolerant of losing a copy. Missense variants: 2,631 observed, 2,680.8 expected, observed/expected ratio (o/e) 0.98, 90% interval 0.95 to 1.01. Synonymous variants: 876 observed, 941.75 expected, observed/expected ratio (o/e) 0.93, 90% interval 0.88 to 0.98.
Gene-disease validity (ClinGen):
ClinGen rates the evidence that RP1 causes each of these diseases.
RP1-related recessive retinopathy (autosomal recessive): Definitive. An autosomal dominant retinopathy caused by variants in the RP1 gene.
Homologues: Orthologues: chimpanzee RP1 (99% identical), macaque RP1 (94% identical), dog RP1 (71% identical), rabbit RP1 (71% identical), pig RP1 (70% identical), mouse Rp1 (60% identical), rat Rp1 (60% identical), Caenorhabditis elegans F27C1.11 (6% identical), zebrafish rp1 (5% identical), Caenorhabditis elegans F27C1.13 (2% identical). Paralogues in human: RP1L1 (13% identical).
Diseases named in the same sentence as RP1 in open-access papers:
RP1 is named in the same sentence as 79 diseases in open-access papers, as found by Europe PMC text mining. Sharing a sentence is not in itself a finding about the gene and the disease. The quoted sentences say what the papers report.
retinitis pigmentosa (32 papers, 2008 to 2026). Retinitis pigmentosa (RP) is an inherited retinal dystrophy leading to progressive loss of the photoreceptors and retinal pigment epithelium and resulting in blindness usually after several decades. "In this study, we investigated the genetic and phenotypic profiles of a cohort of ten Italian retinitis pigmentosa (RP) patients carrying RP1 mutations." (PMID 40136466, 2025). "Mutations in RP1 are a common cause of retinitis pigmentosa, which involves a breakdown and loss of cells in the retina." (PMID 35932226, 2022). "The Retinitis Pigmentosa (RP) is a genetic disorder of the eye that leads to decreased peripheral vision where night blindness is caused by mutation in 50 genes including RP1 gene." (PMID 34980106, 2022). "Molecular diagnosis of AS09 with RP1 mutation (c.3751_3752del, p.Val1251PhefsTer9) led to a revision of the clinical diagnosis as early-onset retinitis pigmentosa." (PMID 33957996, 2021). "Based on the genetic finding, the patient AS09, who harbored a mutation in the RP1 gene, was re-diagnosed with early-onset retinitis pigmentosa." (PMID 33957996, 2021). "Previous studies have shown that the mutation in exon 4 of RP1 causes retinitis pigmentosa in early life, as it encodes 85% of the protein." (PMID 33957996, 2021). "RP1 truncation variants, including frameshift, nonsense, and splicing, are a common cause of retinitis pigmentosa (RP)." (PMID 33681214, 2021). "An extreme example is the RP1 locus, linked to retinitis pigmentosa, in which an additional transcript model containing 22 conserved novel coding exons was added to both the human and mouse gene sets." (PMID 31537640, 2019). "DCX paralogs also include oxygen-regulated protein 1 (RP1), a protein that is mutated in retinitis pigmentosa (a common form of inherited blindness) and whose MT-stabilizing activity is essential for photoreceptor cell development." (PMID 28701917, 2017). "We also found that RPI-1::GFP appears to localise to ciliary and cytoplasmic microtubules, similar to its mammalian orthologue (RP1) implicated in retinitis pigmentosa." (PMID 27930654, 2016). "RP1 variant (NM_006269.1:c.2613dup) was identified in four additional families diagnosed with retinitis pigmentosa." (PMID 27391102, 2016). "Similarly, rhodopsin is mislocalised in Rp1−/− mouse photoreceptors, mutations in RP1 cause Retinitis Pigmentosa 1, and IFT81 has been reported as candidate gene for non-syndromic retinal dystrophy." (PMID 39934925, 2025). "The RP1 gene is known as a causative gene for retinitis pigmentosa (RP)." (PMID 39457414, 2024). "Similarly, RP1 has been shown to localize at the distal part of the CC, similar to lebercilin, and mutations in RP1 lead to retinitis pigmentosa." (PMID 37071472, 2023). "Interestingly, molecular diagnosis identified a homozygous frameshift mutation in exon 4 of the RP1 gene, documented to cause retinitis pigmentosa." (PMID 33957996, 2021). "RP1L1 mutations have been reported to cause a diversity of human photoreceptor diseases that can affect cones and rods, while RP1 mutations have primarily been reported in retinitis pigmentosa cases, although there have been some cone diseases associated with RP1." (PMID 33007938, 2020). "Four RP1 mutations account for the majority of RP1 associated retinitis pigmentosa." (PMID 22131872, 2011). "Summary of RP1 missense mutations identified in patients with retinitis pigmentosa." (PMID 20664799, 2010). "Similarly, the null mutations in exon 4 of RP1 might cause retinitis pigmentosa in the early stages of life." (PMID 33957996, 2021). "Recently, pathogenic variants in the WFS1/RP1/NOD2 genes have been shown to cause congenital cataract, retinitis pigmentosa, and Crohn’s disease in a five generation British family." (PMID 38984127, 2024). "This study also reviewed the fundus characteristics that clinically could raise the hypothesis of a retinitis pigmentosa due to RP1 gene." (PMID 32005865, 2020).
retinitis pigmentosa (continued). "Specifically, we detected pathogenic DNA variants (∼50% novel mutations) in the genes RP1, USH2A, CNGB3, NMNAT1, CHM, and ABCA4, responsible for retinitis pigmentosa, Usher syndrome, achromatopsia, Leber congenital amaurosis, choroideremia, or recessive Stargardt/cone-rod dystrophy cases." (PMID 23940504, 2013). "RP1 completes the triad (RHO, PRPH2, RP1) of genes with highest prevalence for retinitis pigmentosa." (PMID 25506321, 2014). "Furthermore, disease alleles were observed for other autosomal dominantly inherited degenerative diseases of sensory function, including retinitis pigmentosa (SEMA4A, RP1), deafness (MYO1A), glaucoma (CYP1B1, OPTN, WDR36), and keratoconus (VSX1)." (PMID 25333069, 2014).
autosomal dominant retinitis pigmentosa (10 papers, 2006 to 2025). Autosomal dominant retinitis pigmentosa (RP) is an autosomally dominant inherited retinal dystrophy leading to progressive loss of the photoreceptors and retinal pigment epithelium and resulting in blindness usually after several decades. "RP1 mutations are associated with autosomal dominant retinitis pigmentosa but can also cause autosomal recessive forms of the disease." (PMID 40136466, 2025). "To date, at least 170 RP1 mutations have been reported, accounting for approximately 5–10% of autosomal dominant retinitis pigmentosa (ADRP) cases and about 4.5% of autosomal recessive retinitis pigmentosa (ARRP) cases." (PMID 40136466, 2025). "There are at least five genes, RHO, NRL, NR2E3, CRX, and RP1, associated with both autosomal dominant retinitis pigmentosa (ADRP) and autosomal recessive retinitis pigmentosa (ARRP)." (PMID 25692141, 2015). "We also confirmed that RP1, a gene that has been for a long time associated with dominant retinitis pigmentosa, can in fact carry recessive mutations, as previously reported." (PMID 23940504, 2013). "Mutations in the retinitis pigmentosa 1 (RP1) gene are a common cause of autosomal dominant retinitis pigmentosa (adRP), and have also been found to cause autosomal recessive RP (arRP) in a few families." (PMID 22927954, 2012). "For patients with autosomal dominant retinitis pigmentosa (RP), the most frequently associated genes were RHO, RP1, and PRPF31; for X-linked and autosomal recessive forms of RP, the most frequently associated genes were RPGR and USH2A, respectively." (PMID 32423767, 2020). "The other two remained with the diagnosis of RP but turned out to be an X-linked (xlRP) and autosomal dominant retinitis pigmentosa (adRP) with mutations in RP2 (RP-1201) and RP1 (RP-1772) respectively." (PMID 26806561, 2016).
breast carcinoma (10 papers, 2013 to 2025). "Regarding lncRNAs, KLF5 has been reported to regulate LINC0346 in gastric cancer and enhance the expression of RP1 in breast cancer." (PMID 32943987, 2020). "KLF5 is also able to occupy the lncRNA RP1 promoter to enhance RP1 expression, which plays an oncogenic role in breast cancer." (PMID 32460441, 2020). "Rp1 inhibited proliferation of human breast cancer cells such as MCF-7 and MDA-MB-231 through suppression of IGF-1R/pAkt pathway, pAkt of which is also suppressed by Rh2 and aPPD." (PMID 23889969, 2013). "The experiments also revealed that RP1 interacted with the complex p-4E-BP1/eIF4E to attenuate p27kip1 translation, and therefore promote breast cancer metastasis." (PMID 32929060, 2020). "Compounds containing Fc have shown anti-proliferative activity on hormone-dependent breast cancer cell line MCF-7, corroborating with our results that showed the Fc-RP1 interacts with macrophage." (PMID 32214347, 2020). "Furthermore, it has been reported that, during breast cancer metastasis, the transcription factor KLF5 recruits p300 and binds to lncRNA RP1 to enhance the activity of the RP1 promoter, and consequently enhances the RP1 expression." (PMID 32929060, 2020). "Finally, we confirmed the inflammatory profile of neutrophilic cells in CNT-7-treated rats by revealing that these cells weakly expressed Rp-1, a marker of PMN-MDSC in rat mammary carcinoma." (PMID 27549627, 2016).
retinal degeneration (9 papers, 2009 to 2025). Degeneration of the retina. "Among these variants, we described an ancestral frameshift mutation in RP1 which segregates in numerous breeds and causes progressive retinal degeneration." (PMID 27510606, 2016). "It is also evident that the levels of protein delivered for therapy will have to be carefully controlled because over-expression of Rp1 causes retinal degeneration." (PMID 22927954, 2012). "In this study, we present several important insights into the mechanisms by which mutations in RP1 cause retinal degeneration." (PMID 22927954, 2012). "Mice homozygous for the Rp1-Q662X allele experienced progressive retinal degeneration." (PMID 22927954, 2012). "Expression of normal levels of Rp1 protein from the transgene is well tolerated, but lines of transgenic mice that over-express the Rp1 protein experience retinal degeneration." (PMID 22927954, 2012). "Over-expression of Rp1 protein in additional BAC Rp1 transgenic lines resulted in retinal degeneration." (PMID 22927954, 2012). "In both rat retinal degeneration models Rp1 expression is almost completely lost, indicating a near total loss of photoreceptors." (PMID 19680541, 2009). "The literature search found that mutations in the RP1 gene have so far been exclusively associated with a non-syndromic form of retinal degeneration." (PMID 35886928, 2022).
retinal dystrophies (9 papers, 2019 to 2025). "Mutations in RP1 gene are the third leading cause of inherited retinal dystrophies (IRDs) in Pakistani families." (PMID 40029043, 2025). "A recent review documented a total of 15 distinct RP1 variants in Pakistani families with inherited retinal dystrophies (IRDs)." (PMID 40029043, 2025). "Studies focusing on RP1-associated retinal dystrophies in Japanese cohorts further enrich the genotype-phenotype narrative." (PMID 40575766, 2025). "We described the clinical and genetic characteristics of 25 Japanese patients with RP1-associated retinal dystrophies, in whom seven novel variants were identified." (PMID 34073704, 2021). "The Alu element insertion was the most frequently observed pathogenic variant (32.0%, 16/50 alleles) in our Japanese patients with RP1-associated retinal dystrophies." (PMID 34073704, 2021). "Our results have expanded the genetic spectrum and clinical profiles of RP1-associated retinal dystrophies." (PMID 34073704, 2021). "Consistent with this, a previous study on RP1-associated retinal dystrophies indicated oligogenicity in 28 patients with the RP1 variant (p.Arg1933Ter) in one allele, in whom two identified EYS variants were significantly enriched." (PMID 34073704, 2021). "We investigated 25 patients from 23 families with RP1-associated retinal dystrophies, including five patients with AD-RP from five families, 13 patients with AR-RP from 11 families, and seven patients with AR-COD/CORD from seven families." (PMID 34073704, 2021). "In addition, studies on RP1-associated retinal dystrophies in Japan reveal that the clinical features can vary according to the underlying inheritance pattern." (PMID 40575766, 2025). "Therefore, we aimed to clarify the genotype–phenotype correlations and describe the detailed clinical findings of RP1-associated retinal dystrophies." (PMID 34073704, 2021). "However, little is known about the longitudinal findings of patients with AR-COD/CORD, and the genotype–phenotype correlations in RP1-associated retinal dystrophies in the Japanese population." (PMID 34073704, 2021). "This domain-dependent effect on phenotype has been described in a number of other retinal dystrophies, including those associated with RP1 and RHO, which exhibit similar domain-dependent effects on protein function, disease presentation, and patterns of inheritance." (PMID 31856884, 2019). "Genetic etiologies of retinal dystrophy causing both autosomal dominant and recessive disease have been described in the literature and include RHO, RP1, BEST1, GUCY2D, RAX2, and RPE65." (PMID 31856884, 2019). "Detailed genotype-phenotype correlations in RP1-associated retinal dystrophies had not been investigated in the Japanese population." (PMID 34073704, 2021).
autosomal recessive retinitis pigmentosa (5 papers, 2010 to 2025). Autosomal recessive retinitis pigmentosa (RP) is an autosomally recessive inherited retinal dystrophy leading to progressive loss of the photoreceptors and retinal pigment epithelium and resulting in blindness usually after several decades. "We report a previously known pathogenic splice site variant of RP1 as the underlying cause of early-onset autosomal recessive retinitis pigmentosa (arRP) in a Pakistani family." (PMID 40029043, 2025). "Pathogenic variants of RP1 are responsible for both autosomal dominant and autosomal recessive retinitis pigmentosa (ad/arRP)." (PMID 40029043, 2025). "Retinitis pigmentosa 1 (RP1) is a major gene responsible for both autosomal dominant and autosomal recessive retinitis pigmentosa (RP)." (PMID 20664799, 2010).
melanoma (5 papers, 2015 to 2024). A malignant, usually aggressive tumor composed of atypical, neoplastic melanocytes. "The top 10 mutated genes in melanoma were TTN (72%), MUC16 (67%), DNAH5 (49%), PCLO (44%), LRP1B (38%), ANK3 (32%), DNAH7 (32%), ADGRV1 (35%), RP1 (33%), and BRAF (51%)." (PMID 33758620, 2021). "The top 10 mutated genes in 467 melanoma patients are TTN (72%), MUC16 (67%), BRAF (51%), DNAH5 (49%), PCLO (44%), LRP1B (38%), ADGRV1 (35%), RP1 (33%), ANK3 (32%), DNAH7 (32%)." (PMID 33072607, 2020).
prostate carcinoma (5 papers, 2010 to 2023). A carcinoma that arises from epithelial cells of the prostate gland. "On the other hand, LINC00893, LINC01679, MIR22HG, RP1-59D14.5, MAGI2-AS3, NXTAR, FGF14-AS2 and ADAMTS9-AS1 are among lncRNAs that act as tumor suppressors in prostate cancer." (PMID 37025585, 2023).
colon cancer (4 papers, 2010 to 2021). "We explored the effects of Rp1 and ActD on two human colon cancer cell lines, SW620 (drug-sensitive) and LS513 (multidrug-resistant)." (PMID 32151067, 2020). "Treatment of ActD or Rp1 alone mildly inhibited the cell growth while the inhibitory effect of co-administration of Rp1 and ActD was significantly promoted in drug-resistant LS513 colon cancer." (PMID 34975466, 2021).
cone-rod dystrophy (4 papers, 2017 to 2022). Inherited retinal dystrophies that belong to the group of pigmentary retinopathies. "In addition, the RP1 gene has been reported as a cause of the AR-cone dystrophy (COD)/cone-rod dystrophy (CORD) phenotype." (PMID 34073704, 2021). "Difficulties remain in identifying new RP1 mutations as dominant- or recessive-acting, however, as regions of the gene predominately associated with dominant RP were found to also harbour mutations associated with recessive rod-cone dystrophies." (PMID 29099798, 2017). "RP1 variants cause autosomal dominant RP (ADRP), autosomal recessive RP (ARRP), and autosomal recessive cone dystrophy/cone rod dystrophy (AR-COD/CORD)." (PMID 35205402, 2022). "The genetic relatedness of Korean and Japanese populations suggests that founder RP1-Alu insertions may also be found in Koreans with macular dystrophy or cone-rod dystrophy (CRD)." (PMID 34183725, 2021).
Macular dystrophy (4 papers, 2021 to 2024). Macular dystrophy is a nonspecific term for retinal degeneration, generally confined to the macula, usually presumed of genetic origin. "We identified four unsolved cases with macular dystrophy or CRD carrying a single heterozygous truncating mutation in RP1 (NM_006269.1) based on a WES analysis." (PMID 34183725, 2021). "We identified one additional patient (family E) with macular dystrophy previously thought to be unsolved because he harbored only one heterozygous nonsense c.5797C > T variant in RP1." (PMID 34183725, 2021). "To better detect Alu insertions at this location in RP1 in patients with macular dystrophy or CRD, we designed a simple grep search program including the reference sequence (13 bp) and AluY sequence (13 bp) at the junction." (PMID 34183725, 2021). "We also determined the full sequence of the inserted Alu Y. In unsolved early-onset CRD or macular dystrophy, RP1-Alu should be investigated using short-read sequencing data in East Asians." (PMID 34183725, 2021). "Recently, a founder Alu insertion in exon 4 of RP1 has been detected in Japanese patients with macular dystrophy by PCR and gel electrophoresis." (PMID 34183725, 2021). "In addition, a recent study suggested that the phenotypic spectrum associated with RP1 mutations should be expanded to CORD and macular dystrophy." (PMID 33691693, 2021).
retinal disease (4 papers, 2019 to 2025). "A majority of the significantly differentially expressed (FC > 2, FDR < 1%) genes show an increase in expression with higher glucose; these include genes involved in retina development (Neurod1, Casz1, and Crxos) or those associated with retinal disease (Impg1/2, Gucy2f, Mpp4, Arl6, and Rp1)." (PMID 40568109, 2025).